TLR2 (toll like receptor 2)
Diseases named in the same sentence as TLR2 in open-access papers (continued):
Sharing a sentence is not in itself a finding about the gene and the disease.
Sepsis (continued). "Moreover, population studies have shown that TLR2 polymorphisms could influence the body’s overreaction in several diseases such as cancer, tuberculosis, infective endocarditis, and sepsis." (PMID 41598258, 2026). "Adult patients may be at risk for sepsis if they have the TLR2 genotype." (PMID 38685971, 2024). "In addition, a pilot study concluded that the rs5743708 (TLR2) genotype may be a risk factor for sepsis in adult patients." (PMID 36611413, 2022). "Our results conclude that the TLR2 genotype may be a risk factor for sepsis in adult patients." (PMID 36142893, 2022). "Moreover, mortality in sepsis was associated with downregulation of TLR2 levels in blood monocytes." (PMID 35406649, 2022). "Meanwhile, the conducted pilot study concluded that the TLR2 genotype may be a risk factor for sepsis in adult patients, Moreover, our study showed that Asp299Gly polymorphism in TLR4 may be associated with an increased risk of Acinetobacter baumannii infection." (PMID 36142893, 2022). "Interestingly, TLR2 deficient mice are highly susceptible to S. aureus infection, and in humans, a loss-of-function TLR2 mutation has been linked to susceptibility to infectious and inflammatory diseases, faster disease progression, and a more severe course of sepsis in critically ill patients." (PMID 27805901, 2016). "This evidence suggests that TLR2 may be an appealing candidate gene for determining sepsis risk." (PMID 26616674, 2015). "How might the TLR2 Arg753Gln polymorphism affect susceptibility to sepsis?" (PMID 26616674, 2015). "Therefore, we hypothesized that the TLR2 Arg753Gln polymorphism could affect the development of sepsis." (PMID 26616674, 2015). "Several single-nucleotide polymorphisms (SNPs) in TLR2 and TLR4 have been identified in children and adult patients presenting with sepsis and admitted to intensive care units." (PMID 41598258, 2026). "Serum levels of TLR2, TLR4, TLR9, IL-1β, IL-6, IL-8, IL-10, TNF-α and IFN-γ were quantified by enzyme-linked immunosorbent assay at the time of sepsis diagnosis." (PMID 41846925, 2026). "These analyses together with reported literatures 33 indeed confirmed the TLR2 and TLR4 up-regulation as a strong pathogenic factor in sepsis patients." (PMID 40963927, 2025). "(b) TLR2/4-mediated IGFBP6 regulation represents an unexplored mechanistic axis for sepsis progression worthy of further exploration." (PMID 40892465, 2025). "The multifunctional antibacterial drugs that can inhibit both TLR4 and TLR2 signaling pathways to control excessive inflammation are anticipated to be promising therapeutics to treat sepsis." (PMID 40963927, 2025). "In this study, we first performed the bioinformatic analysis on the pediatric and adult septic patient datasets to demonstrate the clinical significance of TLR4 and TLR2 inhibition as a promising therapeutic approach in treating sepsis." (PMID 40963927, 2025). "Through bioinformatic analysis of the pediatric and adult sepsis datasets, we found that the gene expressions of TLR2 and TLR4 were significantly up-regulated in PBMC or blood samples of sepsis patients compared with the healthy controls." (PMID 40963927, 2025). "Three heavily studied TLRs in the context of sepsis include TLR2, TRL4, and TLR9, which are present in lymphocytes and macrophages." (PMID 39968295, 2025). "The results indicate that treatment with rEgAgB had the ability to regulate macrophage polarization possibly through suppressing TLR2 and MyD88 expressions, thus protecting tissues from being injured by the inflammatory storm of sepsis." (PMID 39548530, 2024). "In summary, within a cohort of AML patients following induction chemotherapy, it was observed that polymorphisms of TLR2 and TLR4 influence the risk of developing sepsis and pneumonia." (PMID 38982248, 2024). "Numerous reports on sepsis highlight the importance of TLR2, TLR3, and TLR4 in cardiac dysfunction and cardiomyopathy, although their precise roles remain incompletely understood." (PMID 39201339, 2024).
Sepsis (continued). "The presence of a specific IRAK-1 variant haplotype, a crucial protein in the TLR2 and TLR4 pathway, is linked to increased nuclear translocation of NF-κB, contributing to a worse prognostic clinical presentation in sepsis." (PMID 38835761, 2024). "Alleviating sepsis through activating M2 phenotypic macrophages mediated by inhibiting the TLR2/MYD88 signaling pathway." (PMID 39314046, 2024). "Consistent with findings in sepsis and other cardiomyopathy models, TLR2 KO and TLR3 KO are shown to be protective, whereas TLR4 KO exacerbates cardiac dysfunction and cardiomyopathy." (PMID 39201339, 2024). "T. spiralis cystatin (TsCys) derived from adult worms also alleviated inflammatory models like sepsis by activating M2 phenotypic macrophages mediated by inhibiting the TLR2/MYD88 signaling pathway." (PMID 39314046, 2024). "Consistent with previous data, using the experimental model of polymicrobial sepsis induced by cecal ligation and puncture, one group showed increased TLR2 levels in the kidney and intestine." (PMID 37569837, 2023). "HMGB1 acts as an endogenous damage-associated molecular pattern (DAMP) that triggers the innate immune response via binding to toll-like receptor 2 (TLR2), TLR4, and TLR9, which contributes to infection-induced sepsis caused by several pathogens." (PMID 38022511, 2023). "TLR2 appears to be a therapeutic target for suppressing inflammatory activity and protecting cardiac function in old subject in sepsis." (PMID 38094127, 2023). "Studies have shown that TLR2 is a major signaling sensor for recognizing microbial infections and is involved in the pathogenesis of sepsis." (PMID 38066526, 2023). "To evaluate the role of TLR2 in age-related inflammatory response to sepsis, we analyzed inflammatory cytokines in the myocardium and plasma of WT and TLR2 KO mice of different age." (PMID 38094127, 2023). "TLR2 is a component of the innate immune system and plays a crucial role in mediating inflammatory response to polymicrobial sepsis." (PMID 38094127, 2023). "Male young adult (4–6 months) and old (18–20 months) wild type (WT) and TLR2 knockout (KO) mice were subject to moderate sepsis by cecal ligation and puncture." (PMID 38094127, 2023). "This indicates that a single dose of TLR2 agonist elicits an inflammatory response lasting for a shorter time while sepsis induces a longer-lasting inflammatory response through sustained TLR2 stimulation by bacterial products." (PMID 38094127, 2023). "Previous studies have shown that aging is an independent predictor of mortality in sepsis, and elevated TLR2 activity in the aging heart exacerbates myocardial inflammatory activity." (PMID 38094127, 2023). "Although TLR signaling is essential for host defense, persistent activation of TLRs, particularly TLR2, and related signaling pathways during sepsis would result in dysregulated systemic inflammatory responses." (PMID 38094127, 2023). "TLR2 can recognize a wide variety of pathogens and is responsible for the inflammatory cascade in sepsis." (PMID 35960478, 2023). "Aging elevates TLR2 level/activity to exacerbate the inflammatory response to sepsis, leading to worse cardiac dysfunction and mortality." (PMID 38094127, 2023). "We observed in a previous study that aging elevates myocardial TLR2 levels, indicating that elevated TLR2 activity in aging heart augments myocardial inflammatory responses to sepsis." (PMID 38094127, 2023). "It has been shown that Streptococcus pneumoniae induces platelet activation via TLR2 and that its inhibition completely abolished platelet aggregation, implicating TLR2 in the thrombotic complications of sepsis." (PMID 37569837, 2023). "TLR2 KO reduced inflammatory cytokine levels in the myocardium and plasma of both young adult and old mice with sepsis." (PMID 38094127, 2023). "Eight genes (CLEC5A, MALT1, NAIP, NLRC4, SERPINB1, SIRT1, STAT3, and TLR2) related to sepsis diagnosis were screened by multiple machine learning algorithms." (PMID 36817458, 2023).
Sepsis (continued). "TLR2 and 4 are the two sponsors to the pathogenesis of sepsis.Thus, manipulation of TLR signaling pathways has been predicted to be an effective therapeutic strategy for sepsis." (PMID 37465127, 2023). "The up-regulation of TLR4, TLR2, CD62P, and CD32 has been described in sepsis and is associated with an increased ability to bind E. coli bacteria." (PMID 36769137, 2023). "Taken together, these findings underscore the multifaceted role of TLR2 in the hyperinflammatory state and also in sepsis-induced immunosuppression." (PMID 37569837, 2023). "Intriguingly, aging played a dominant role in sepsis deaths compared with TLR2, as WT/old and TLR2−/−/old mice both had similar mortality rates." (PMID 36808423, 2023). "The findings support the concept that elevated TLR2 level exacerbates the inflammatory activity to drive the severity of cardiac dysfunction in old subjects with sepsis." (PMID 38094127, 2023). "Future studies are needed to identify TLR2-independent mechanism that contributes to aging-related exacerbation of inflammation in sepsis." (PMID 38094127, 2023). "In this study, we aimed to investigate the possible role of TLR2 and TLR4 polymorphisms in affecting sepsis susceptibility and survival in critically ill patients in the Egyptian population using both in silico analysis and experimental methods." (PMID 36142893, 2022). "We identified cell-intrinsic signaling through TLR2 as the origin of impaired IFN-γ synthesis by CD8+ T cells during sepsis that unexpectedly limited the dysregulation of differentiating DCs in the BM." (PMID 36148245, 2022). "The migration of neutrophils to the kidney during sepsis is dependent on the activation of TLR2, TLR4 and the adapter molecule-MyD88." (PMID 36010680, 2022). "The current study aimed to investigate the association of genetic polymorphisms of the TLR2 and TLR4 with the risk of developing sepsis with both a pilot study and in silico tools." (PMID 36142893, 2022). "The use of TLR2 as therapeutic targets against infections and sepsis have been summarized in a recent review." (PMID 35986268, 2022). "For example, it is well known that TLR4 and TLR2 play an important role in mediating the development in sepsis-induced myocardial injury." (PMID 35721566, 2022). "Unexpectedly, CD8+ T cells in the BM of WT mice decreased their expression of PD-1 during sepsis, whereas the expression of PD-1 remained unchanged in TLR2−/− mice." (PMID 36148245, 2022). "The nuclear protein high mobility group box 1 protein (HMGB1) is also released during severe COVID-19, ALI/ARDS and sepsis and drives TLR2 and TLR4 activation." (PMID 33672738, 2021). "Our data are in line with the literature, describing the participation of SAA1 in the inflammatory response of TLR2/4 activation in periodontitis, myotube atrophy, or sepsis, among others." (PMID 34070533, 2021). "For example, TLR2 is associated with systemic lupus erythematosus (SLE), sepsis, psoriasis; TLR3 with sepsis; TLR4 with SLE, sepsis, and psoriasis; TLR5 with psoriasis; TLR7 with SLE, stroke, and psoriasis; and TLR9 is involved in SLE, sepsis and psoriasis." (PMID 34203170, 2021). "Our results further confirm that severe infection of bacteria in sepsis stimulates inflammatory immune responses through HMGB1/TLR2/MyD88 activation signal pathway as shown for other helminth-derived proteins." (PMID 33842398, 2021). "Severe COVID-19, ALI/ARDS and sepsis patients are all characterized by the activation and increased expression of TLR2, TLR4 and NOD2 (and sometimes NOD1, as well) and their associated synergisms (which are quite numerous)." (PMID 33672738, 2021). "For instance, in Burkholderia infection, knockout of TLR2 enhances the survival of mice and reduces sepsis, compared to what was observed with wild-type mice." (PMID 34933448, 2021).
Sepsis (continued). "Whereas TLR2 antagonists are primarily being utilized to prevent symptoms of sepsis, a wide variety of TLR2 agonists have been used to amplify the immune response in several models of infection, vaccination or antitumor immunity." (PMID 32696994, 2020). "KCNQ1OT1, the lncRNA having putative RNA–RNA interaction with TLR2, was found to attenuate sepsis-induced myocardial injury via regulating miR-192-5p/XIAP axis." (PMID 33224264, 2020). "Some human studies on TLR2 expression in sepsis patients have reported that TLR2 is upregulated in sepsis patients and down-regulated in severe sepsis and septic shock patients, leading to death." (PMID 33256638, 2020). "We also measured mRNA levels of Neurod1 and Klf4, which were downregulated in the sepsis group, and levels of Tlr2, which were upregulated in the sepsis group." (PMID 33200654, 2020). "In this study, we investigated the impact of TLR2 and TLR4 SNPs on susceptibility of AML patients towards developing sepsis, pneumonia and fever during severe neutropenia following intensive chemotherapy as well as its impact on the patient’s outcome." (PMID 33247673, 2020). "Here, we show that TLR-2 and −4 agonists trigger ATP-release via Connexin-43 hemichannels in macrophages leading to poor sepsis survival." (PMID 30735126, 2019). "The 185 subgroup meta-analyses by ethnicity and age revealed three additive polymorphisms (TLR2 rs5743708 Arg753Gln, IL6 rs1800796-572G/C, and IL10 rs1800896-1082A/G) that were significantly associated with the risk of sepsis." (PMID 30683156, 2019). "T2.5, a neutralizing antibody against TLR2, has been shown to prevent sepsis induced by TLR2 ligands." (PMID 31998072, 2019). "As seen in whole blood samples from sepsis patients, TLR2 induction correlated with the overexpression of genes associated with immunosuppression (IL10, FPR2) or wound healing (MMP9)." (PMID 31396208, 2019). "Previous experiments have confirmed that extracellular HMGB1 is a lethal inflammatory mediator in late sepsis as it activates the inflammation-related signalling pathways by binding with its specific receptors RAGEs/TLR-2/TLR-4." (PMID 31781288, 2019). "The lipoxin A4 agonist, BML-111, alters the expression of TLR2 and 4 in a murine cecal ligation/puncture model of sepsis with improvements in pro-inflammatory IL-6 and TNF-α production." (PMID 29515999, 2018). "In the setting of polymicrobial sepsis, most studies in the past investigated the role of TLR2 and TLR4 as mediating a systemic inflammatory response." (PMID 30364002, 2018). "In German adult patients with Candida sepsis, the heterozygotic status in TLR2 2258 G>A SNP was correlated with altered cytokine release, including increased plasma concentrations of TNF-α and decreased levels of IFN-γ and IL8." (PMID 28118851, 2017). "Other TLR-related genes (TLR2, 3, and 9) were demonstrated to be involved in sepsis-induced cardiac dysfunction from recent studies." (PMID 28970829, 2017). "Studies also have shown that blocking TLR2 or TLR4 resulted in decreasing disease severity in sepsis." (PMID 28056977, 2017). "Apoptosis, a major cause for DC depletion, was significantly enhanced in lethal sepsis, which was further identified as TLR2 and TLR4 dependent, since it was prevented in TLR2−/− and TLR4−/− mice." (PMID 29326712, 2017). "TLR2 and TLR4 were significantly up regulated in sepsis caused by other pathogens compared to healthy controls." (PMID 28628607, 2017). "Altogether, these proof-of-principle studies suggest that blocking TLR2 signaling is therapeutically beneficial to sepsis and vascular system disorders." (PMID 28769820, 2017). "Melioidosis patients showed significantly down regulated expression of TLR4 while both TLR2 and TLR4 was down regulated in septicaemic melioidosis cases compared to sepsis caused by other pathogens." (PMID 28628607, 2017).
Sepsis (continued). "Modulation of the monocyte response during sepsis occurred despite preservation of LPS binding to monocytes and of TLR2 and TLR4 expression on the monocyte cell surface." (PMID 26879814, 2016). "It was demonstrated that CCR2 is induced on the neutrophil surface in mice and patients with sepsis in a TLR2- or TLR4-dependent manner." (PMID 27199981, 2016). "Corroborating these data, tlr2-, 4-, and 9-deficient mice show an increase in CXCR2 expression on circulating neutrophils, compared with WT mice subjected to severe sepsis." (PMID 27199981, 2016). "Pretreatment with TLR2 agonist Pam3Cys, a synthetic ligand of TLR2 and TLR1, attenuated the sepsis-induced cytokine burst and protected mice from polymicrobia peritonitis, suggesting that ligands of TLR2 enhance immune responses against bacteria." (PMID 26974438, 2016). "Accordingly, PSMs have a strong impact on the severity of sepsis, and TLR2 has an important role in systemic S. aureus infections only for PSM-producing strains." (PMID 27470911, 2016). "The role played by human protein TLR2 in inflammation and sepsis varies for different bacterial pathogens." (PMID 27470911, 2016). "Previous studies by our group showed that either TLR2- or TLR4-deficient mice display improved bacterial clearance and reduced mortality during polymicrobial sepsis." (PMID 26147469, 2015). "Relevance of endotoxin tolerance and TLR hyporesponsiveness by TLR2-specific ligands have been previously shown in sepsis models and bacterial challenge infections." (PMID 25611587, 2015). "Here, we evaluated the effects of preventive or therapeutic administration of monoclonal antibodies (mAbs) targeting either TLR2 or TLR4 in a model of severe polymicrobial sepsis induced by cecal ligation and puncture in mice." (PMID 26147469, 2015). "Subsequent transfer improved sepsis outcome in naïve mice in a Wolbachia- and TLR2-dependent manner." (PMID 25611587, 2015). "No IL-17A induction was observed in placebo or morphine-treated CLP TLR2KO animals, strongly implying that TLR2 plays a role in IL-17A responses in CLP-induced sepsis." (PMID 26039416, 2015). "TLR2 also plays a critical role in mediating mitochondrial dysfunction in peritoneal leukocytes, during polymicrobial sepsis." (PMID 26599367, 2015). "Until now, little was known about the relationship of MFHAS1 and sepsis, and the mechanisms underlying the effect of MFHAS1 on the TLR2 signaling pathway and inflammation." (PMID 26599367, 2015). "The aim of this present study is to investigate the relationship of MFHAS1 and sepsis, and the effects of MFHAS1 on the TLR2 signaling pathway and inflammation, and highlight this protein as an optional target in the treatment of inflammation in sepsis." (PMID 26599367, 2015). "Recently, researchers in a number of studies have explored the association between the Toll-like receptor 2 (TLR2) Arg753Gln polymorphism and sepsis risk." (PMID 26616674, 2015). "In our sepsis model, dendritic cells expressing TLR2 were required for a robust IL-17A response, which was mediated by IL-1β and IL-23." (PMID 26039416, 2015). "Taken together, these experiments demonstrate that the L. sigmodontis-mediated protective effects against an E. coli-induced sepsis are dependent on TLR2 signaling." (PMID 25611587, 2015). "Even though several TLRs are known to cause sepsis, the vast structural and functional information make TLR4 the most attractive target and TLR2 the next favorite for anti-sepsis treatment." (PMID 26198237, 2015). "Parasite burden was also unaltered between TLR2-deficient and wild type BALB/c mice, excluding the possibility that differences in L. sigmodontis baseline levels were the cause for the reverted sepsis phenotype." (PMID 25611587, 2015). "Toll-like receptors (TLR) signaling like TLR4 and TLR2 is the key pathway in sepsis pathophysiology." (PMID 25054155, 2014).